CRB3 (crumbs cell polarity complex component 3)
Description:
Involved in the establishment of cell polarity in mammalian epithelial cells. Regulates the morphogenesis of tight junctions. Involved in promoting phosphorylation and cytoplasmic retention of transcriptional coactivators YAP1 and WWTR1/TAZ which leads to suppression of TGFB1-dependent transcription of target genes such as CCN2/CTGF, SERPINE1/PAI1, SNAI1/SNAIL1 and SMAD7 (By similarity).
Synonyms: MGC17303
Tractability: Antibody: UniProt places it where antibodies can reach, with high confidence; its Gene Ontology location is reachable by antibodies, with high confidence; UniProt predicts a signal peptide or a membrane-spanning region.
Gene: Protein-coding gene on chromosome 19 (6,463,777 to 6,467,221, forward strand). Ensembl gene ENSG00000130545.
Subcellular location: Apical cell membrane; Cell junction, tight junction
Subcellular location (Human Protein Atlas): Cell Junctions
Pathways (Reactome):
Cell-Cell communication: Tight junction interactions
Disease: SARS-CoV-2 targets PDZ proteins in cell-cell junction
Gene Ontology:
Molecular function: protein binding; protein domain specific binding; SH3 domain binding
Biological process: protein localization to plasma membrane; tight junction organization; establishment or maintenance of epithelial cell apical/basal polarity; positive regulation of cell junction assembly
Cellular component: apical plasma membrane; cell junction; extracellular exosome; tight junction; apical junction complex; plasma membrane; apical part of cell; bicellular tight junction; protein-containing complex; subapical complex
Genetic constraint (gnomAD): Loss-of-function variants: 4 observed, 6.62 expected, observed/expected ratio (o/e) 0.6, 90% interval 0.3 to 1.37. That is too few expected variants to judge how well the gene tolerates losing a copy. Missense variants: 151 observed, 144.91 expected, observed/expected ratio (o/e) 1.04, 90% interval 0.91 to 1.19. Synonymous variants: 73 observed, 62.98 expected, observed/expected ratio (o/e) 1.16, 90% interval 0.96 to 1.41.
Homologues: Orthologues: chimpanzee CRB3 (87% identical), macaque CRB3 (72% identical), pig CRB3 (70% identical), dog CRB3 (68% identical), guinea pig CRB3 (56% identical), rat Crb3 (54% identical), mouse Crb3 (51% identical), tropical clawed frog crb3 (32% identical). Paralogues in human: CRB2 (33% identical), SCARF2 (18% identical), SCARF1 (14% identical).
Diseases named in the same sentence as CRB3 in open-access papers:
CRB3 is named in the same sentence as 29 diseases in open-access papers, as found by Europe PMC text mining. Sharing a sentence is not in itself a finding about the gene and the disease. The quoted sentences say what the papers report.
breast carcinoma (7 papers, 2017 to 2023). "We previously reported that CRB3 expression was high in immortalized mammary epithelial cells, whereas loss of CRB3 expression was observed in breast cancer cells." (PMID 37737843, 2023). "We found that CRB3 expression was negatively correlated with tamoxifen resistance in breast cancer patients and that tamoxifen‐resistant cells which overexpress CRB3 were more susceptible to tamoxifen treatment, reduced self‐renewal capability and suppressed the Wnt signalling pathway." (PMID 29602199, 2018). "Furthermore, these findings indicate that CRB3 is an important regulator for breast cancer stemness, which is associated with tamoxifen resistance." (PMID 29602199, 2018). "Consistent with the observations in breast cancer tissues, there was an inverse association between expression level of CRB3 protein and expression levels of β‐catenin protein, β‐catenin downstream factors (CD44 and cMyc) and cancer stem cell‐associated transcription factors (OCT4 and NANOG)." (PMID 29602199, 2018). "In the future, understanding of how CRB3 is deregulated during the initiation and progression of breast cancer may lead to new diagnostic and therapeutic opportunities for breast cancer." (PMID 28436991, 2017). "Defects in CRB3 expression inhibit ciliary assembly in breast cancer tissues and activate the Wnt signaling pathway in mammary cells and PyMT mouse model." (PMID 37737843, 2023). "To investigate the role of Crb3 in breast cancer tumorigenesis, we observed mammary glands from 9-week-old virgin polyomavirus middle T antigen (PyMT)-cKO-Crb3 and PyMT-WT mice." (PMID 37737843, 2023). "To investigate the role of CRB3 in regulating ciliary assembly in breast cancer, we examined the relationship between CRB3 and the primary cilium in breast cancer tissues." (PMID 37737843, 2023). "CRB3 is closely related to the occurrence of some tumors such as colorectal carcinoma, breast cancer and oral squamous cell carcinomas and CRB3 affects the occurrence of these diseases by regulating the Hippo pathway." (PMID 38049890, 2023). "We also identified that CRB3 regulates the ciliary Hedgehog (Hh) and Wnt signaling pathways in breast cancer." (PMID 37737843, 2023). "Our previous studies have shown that CRB3 is expressed at low levels in renal and breast cancers, and abnormal CRB3 expression leads to the disrupted organization of MCF10A cells in three-dimensional (3D) cultures." (PMID 37737843, 2023). "Another study conducted in breast cancer cells further supports the presence of SNAIL-independent regulatory mechanisms of CRB3 expression." (PMID 34830224, 2021). "E-box sequences can be bound by other transcription factors, including ZEB-1, which has been shown to repress LLGL2, PATJ, and CRB3 in a breast cancer cell line." (PMID 34830224, 2021). "Increased CRB3 expression resumes the response of tamoxifen‐resistant cells to tamoxifen by suppressing breast cancer stem cell‐like features through blocking β‐catenin signalling." (PMID 29602199, 2018). "In aggregate, these results demonstrated that elevated CRB3 expression inhibits stemness of tamoxifen‐resistant breast cancer cells." (PMID 29602199, 2018). "Our previous study indicated that decreased expression of the CRB3 gene confers stem cell characteristics to breast cancer cells." (PMID 29602199, 2018). "We found that CRB3 knockdown upregulated CSC-TFs in MCF 10A breast epithelial cells, whereas CRB3 overexpression supressed CSC-TFs in MM231 breast cancer cells." (PMID 28436991, 2017). "CRB3 expression was significantly lower in breast cancer cells than in immortalized mammary epithelial cells, regardless of cell density." (PMID 28079891, 2017). "The expression levels of the CRB3 mRNA and protein were significantly lower in breast cancer cells than in immortalized mammary epithelial cells." (PMID 28079891, 2017). "One possible explanation is that CRB3 was expressed at significantly higher levels in MCF10A cells than in other breast cancer cells." (PMID 28079891, 2017).
breast carcinoma (continued). "We examined CRB3 expression in breast cancer tissues and cells to investigate the role of CRB3 in breast cancer." (PMID 28079891, 2017). "In this study, we found that CRB3 was strongly expressed in normal breast epithelial tissues, but weakly expressed in breast cancer tissues." (PMID 28436991, 2017). "We next determined CRB3 expression levels in normal breast and breast cancer tissues by immunohistochemistry." (PMID 28436991, 2017). "This study is the first to investigate the relationship between CRB3 expression and the clinicopathological features of breast cancer patients." (PMID 28436991, 2017). "(A) Representative immunofluorescent images of CRB3 in breast cancer tissues (n = 50)." (PMID 37737843, 2023). "Furthermore, CRB3 is regulated by the transcription factor estrogen receptor α (ERα) in breast cancer cells." (PMID 34830224, 2021). "These expression patterns strongly suggested that CRB3 and β‐catenin might be involved in tamoxifen resistance of breast cancer." (PMID 29602199, 2018). "To study whether CRB3 expression plays a role in tamoxifen resistance in breast cancer, we examined nine pairs of breast cancer tissues resistant to tamoxifen and matched primary tumours." (PMID 29602199, 2018). "CRB3 overexpression inhibited breast cancer cell proliferation and induced cell apoptosis in vitro." (PMID 28079891, 2017). "CRB3 expression was low in breast cancer tissues but was high in adjacent normal breast tissues." (PMID 28079891, 2017). "Moreover, we found that Crb3 deletion promotes breast cancer progression in vivo." (PMID 37737843, 2023). "Finally, we found that CRB3 suppressed the stemness of TamR cells by inhibiting β‐catenin signalling, which may in turn lead to a decrease in the breast cancer cell population." (PMID 29602199, 2018). "Based on these data, CRB3 overexpression may be a therapeutic approach for breast cancer treatment." (PMID 28079891, 2017). "Among the breast cancer cell lines, MCF7 showed the higher CRB3 mRNA and protein expression levels, followed by T-47D, BT-474, MM231 and MM453, in descending order." (PMID 28436991, 2017). "We found that CRB3 was localized at the subapical surface of the mammary gland lumen in the paracarcinoma tissues, but no obvious expression or localization in breast cancer tissues." (PMID 37737843, 2023). "In the current investigation, we found that most of the breast cancer patient tissues resistant to tamoxifen were negative for CRB3 protein and positive for β‐catenin protein, in contrast to their matched primary tumours by immunohistochemical analysis." (PMID 29602199, 2018). "Interestingly, while this binding leads to repression of transcription in MDCK cells, it does not constitutively result in CRB3 repression in breast cancer cells." (PMID 34830224, 2021). "Here, we detected significantly lower or negative CRB3 expression in human breast cancer tissues." (PMID 28436991, 2017). "To investigate whether CRB3 regulates the tamoxifen sensitivity of breast cancer cells by suppressing tamoxifen‐resistant cells from acquiring stem cell‐like characteristics, we examined cancer stem cell (CSC) properties of breast cancer cells whose CRB3 expression was altered." (PMID 29602199, 2018). "To investigate CRB3 expression in human mammary epithelial cells, we examined CRB3 mRNA and protein levels in a non-tumorigenic cell line (MCF 10A) and five breast cancer cell lines (MCF7, T-47D, BT-474, MDA-MB-231(MM231) and MDA-MB-453(MM453))." (PMID 28436991, 2017).
cystic kidneys (3 papers, 2015 to 2023). "Moreover, we showed that the expression level of Par3 and aPKC is reduced in Crb3-deficient renal cyst cells, and that aPKC is mislocalized in tubules prior to cyst formation." (PMID 26631503, 2015). "Moreover, our data have demonstrated that Crb3 knockout mice suffer from ectopic accumulation of mucosubstances in lungs, develop cystic kidneys and display fusion of villi in the intestine." (PMID 26631503, 2015).
ciliopathies (2 papers, 2015 to 2023). "In particular, the phenotypes of CEP290-associated ciliopathies are very similar to those in our Crb3 knockout mouse model, with lethality and ocular and renal abnormalities." (PMID 37737843, 2023). "Although additional studies are required to define the mechanisms by which Crb3 maintains the homeostasis and physiology of the kidney epithelium, our data clearly establish that further deciphering of Crb3 functions is crucial for understanding PKD, and perhaps other ciliopathies." (PMID 26631503, 2015).
cyst (2 papers, 2015 to 2021). A sac-like closed membranous structure that may be empty or contain fluid or amorphous material. "Therefore, loss of function of CRB3 could potentially be linked to cyst formation and/or fibrosis." (PMID 34868264, 2021). "CRB3 protein plays an important role in apicobasal polarity formation, such as cyst formation." (PMID 34868264, 2021). "Similarly, the apical distribution of Par3 and aPKC was preserved in tubules devoid of Crb3 (red arrowhead), but these proteins were barely detectable at the apical domain of cyst cells (arrow)." (PMID 26631503, 2015).
retinal disease (2 papers, 2017 to 2025). "Another CRB1 paralog, CRB3, localizes to the Müller glial cells, photoreceptors, rod bipolar cells, and vascular pericytes, but variants in this gene have yet to be linked to retinal disease." (PMID 40590804, 2025). "Finally, although CRB3 mRNA has been found in the macula and peripheral retina, the CRB3 gene has yet to be linked to retinal disease." (PMID 28424578, 2017).
adenoma (1 paper, 2022). A neoplasm arising from the epithelium. "In the present study, we discovered that CRB3 levels in both adenoma and CRC were substantially lower than in normal tissues, and we also revealed that patients with CRC with high CRB3 level exhibited higher overall survival and disease-free survival." (PMID 35012593, 2022). "Our results also indicated that CRB3 level was substantially lower in the adenoma and CRC groups than in the normal group, which was consistent with the data from TCGA database." (PMID 35012593, 2022). "The results indicated that the expression of YTHDF2 was also significantly higher in adenoma and CRC tissues relative to normal tissues, and YTHDF2 knockdown substantially increased the level of CRB3." (PMID 35012593, 2022).
bladder cancer (1 paper, 2025). "Similarly, combination treatment with a silk-hydrogel encapsulated Adv-CRB3 (Adv-CRB3@gel, armed with CRB3 and GM-CSF) and an anti PD-L1 antibody significantly reduced tumor size in a subcutaneous bladder cancer mouse model." (PMID 41445946, 2025).
Blindness (1 paper, 2017). Blindness is the condition of lacking visual perception defined as a profound reduction in visual perception. "Interestingly, mutations in human CRB1 result in RP12-asssociated blindness, despite the fact that CRB2 and CRB3 are also expressed in the retina." (PMID 28202468, 2017).
cervical carcinoma (1 paper, 2015). A carcinoma arising from either the exocervical squamous epithelium or the endocervical glandular epithelium. "And in cervical carcinoma cells, over-expression of the mammalian CRB3 protein restores an epithelial-like morphology by organising a cortical actomyosin network through the regulation of the p114RhoGEF-RhoA-ROCK1/2 pathway via the FERM protein Ehm2." (PMID 26544546, 2015).
clear cell renal cell carcinoma (1 paper, 2020). "But its homolog protein CRB3 may mediate the extracellular signal transduction in clear cell renal cell carcinoma development via an intracellular signal, such as Hippo signal." (PMID 32596394, 2020).
colon cancer (1 paper, 2015). "Moreover, our study provides evidence that Crb3 limits accumulation of cytoplasmic β-catenin in the intestine, thereby suggesting that Crb3 dysfunctions could predispose to colon cancer." (PMID 26631503, 2015).
Immunodeficiency (1 paper, 2017). Failure of the immune system to protect the body adequately from infection, due to the absence or insufficiency of some component process or substance. "To verify CRB3 effects on CSCs in vivo, we injected Vector-infected MM231(left) or CRB3-overexpressing MM231(right) cells into the fat pad of severe combined immunodeficiency mice." (PMID 28436991, 2017).
metastatic tumor (1 paper, 2021). "In addition, we explored the roles of CRB3 and GET4 in pancancer screening on the "Data explorer" module of the DepMap database, including RCC and non-RCC, MSI and MSS, and primary and metastatic tumor cell lines." (PMID 33850477, 2021).
osteoarthritis (1 paper, 2023). A noninflammatory degenerative joint disease occurring chiefly in older persons, characterized by degeneration of the articular cartilage, hypertrophy of bone at the margins and changes in the synovial membrane. "CRB3 could affect Hippo pathway and some study showed that Hippo pathway contributed to osteoarthritis and that it could regulate the glycometabolism in mice." (PMID 38049890, 2023).
polycystic kidney disease (1 paper, 2015). A usually autosomal dominant and less frequently autosomal recessive genetic disorder characterized by the presence of numerous cysts in the kidneys leading to end-stage renal failure. "In addition to clarifying the physiologic roles of Crb3, our study highlights that further functional analysis of this protein is likely to provide insights into the etiology of diverse pathologies, including respiratory distress syndrome, polycystic kidney disease and cancer." (PMID 26631503, 2015).
renal failure (1 paper, 2015). "Thus, in addition to providing crucial insights into the function of Crb3 in vivo, the availability of our mouse model to the research community will contribute to the understanding of pathologies associated with polarity defects, including cancer and renal failure." (PMID 26631503, 2015).
squamous cell carcinoma (1 paper, 2025). A carcinoma arising from squamous epithelial cells. "Interestingly, CRB3 promotes activation of RhoA by interacting with RhoGEF proteins (such as Cysts in Drosophila) to drive apical constriction; conversely, loss of CRB3 reduces active Rho, resulting in decreased cell migration and contractility in squamous cell carcinomas." (PMID 41122968, 2025).
staphylococcus aureus infection (1 paper, 2020). An infectious process in which the bacteria Staphylococcus aureus is present. "The expression patterns of proteins involved in the tight junction pathway (related genes: Tuba, PAR6, AMPK, Myosin II, CRB3, JARB, and ZO-3) and Staphylococcus aureus infection pathway (related genes: PLG and KRT1) also show synergistic regulation effects of GA and GKW." (PMID 32765254, 2020).